FAT1 (FAT atypical cadherin 1)
Diseases named in the same sentence as FAT1 in open-access papers (continued):
Sharing a sentence is not in itself a finding about the gene and the disease.
coloboma (4 papers, 2019 to 2025). An abnormality in which a part of a structure in one or both eyes is missing. "A recent study described a homozygous frameshift variant in FAT1 in connection with microphthalmia or coloboma and syndromic features in five families and demonstrated its implication in optic cup development in a mouse model." (PMID 41155148, 2025). "The causality of FAT1 loss of function mutations and coloboma was demonstrated in zebrafish by fat1a knockdown and homozygous fat1a frameshift mutants, both of which resulted in coloboma." (PMID 33418956, 2021). "We demonstrate that Fat1 knock-out mice and zebrafish homozygous for truncating fat1a mutations exhibit coloboma, supporting the causality of these mutations and pointing to an evolutionary conserved role of Fat1 in eye development and optic fissure closure." (PMID 30862798, 2019). "We here report five unrelated families exhibiting a syndromic form of coloboma associated with homozygous frame-shift mutations in the FAT1 gene." (PMID 30862798, 2019). "The causal relation between loss of function mutations in FAT1 and coloboma was established through studies in mice and fish loss-of-function models, underscoring a highly conserved role of FAT1 during vertebrate eye development." (PMID 30862798, 2019). "Our mechanistic studies in mice, zebrafish, and RPE cell cultures support the causality of FAT1 biallellic frameshift variants in the pathogenesis of coloboma, and for the first time implicate FAT1 in optic fissure fusion during eye development." (PMID 30862798, 2019). "Here, the authors report five families with a syndromic form of coloboma associated with homozygous frameshift variants in FAT1 and recapitulate the phenotype in mutant mice and zebrafish." (PMID 30862798, 2019). "Coloboma and syndactyly present in index patient 3[II:1] are consistent with the clinical features seen in the new FAT1-associated multisystemic disorder, which is characterized by colobomatous microphthalmia, facial dysmorphism, ptosis, syndactyly, and occasional glomerulotubular nephropathy." (PMID 33418956, 2021). "Overall, we assume that the compound heterozygous frameshift variant and deletion in FAT1 lead to the loss of FAT1 protein, which results in developmental eye anomalies such as coloboma and cataract, syndactyly, and hearing impairment, as seen in index patient 3[II:1]." (PMID 33418956, 2021). "Variants in other members of this family, FAT1 and FAT2, were found to be associated with recessive syndromic ocular coloboma and dominant spinocerebellar ataxia-45." (PMID 35885948, 2022). "Previous studies have suggested the association of coloboma with β-CATENIN19, RERE20, and SCRIBBLE21; currently we do not know which of these proteins are involved in FAT1-mediated coloboma." (PMID 30862798, 2019). "In support of this hypothesis, Fat1−/− knockout mice display coloboma, microphthalmia, and anophthalmia with incomplete penetrance, whereas the eyes of Fat1−/+ mice appear normal, indicating that heterozygous Fat1 depletion does not affect eye formation." (PMID 33418956, 2021).
diabetes (4 papers, 2014 to 2022). "In our latest published report using the spontaneous type 1 diabetic NOD mice, an EPA/DHA-enriched diet and a fat-1 gene therapy not only delayed the onset but also reversed the autoimmunity and diabetes." (PMID 31611873, 2019). "Incorporating the fat-1 transgene in the diabetes context, or oral MEDICA treatment, resulted in ameliorating the diabetic phenotype and in abrogating CRC, with decrease in ACF load, cell proliferation and the expression of HNF-4α, β-catenin, and β-catenin-responsive genes." (PMID 25375205, 2014). "Most importantly, introducing the fat-1 gene into the diabetes context resulted in abrogating CRC development and cell proliferation, while suppressing the expression of HNF-4α, β-catenin and β-catenin/Tcf-responsive genes, and promoting epithelial differentiation." (PMID 25375205, 2014). "Most importantly, introducing the fat-1 gene into the db/db context resulted in reverting the aberrant foci load to the fat-1 score, both in terms of the overall load as well as the microadenoma prevalence, implying resistance to DMH-induced diabetes-promoted CRC by (n-3) PUFA." (PMID 25375205, 2014).
esophageal cancer (4 papers, 2015 to 2024). A primary or metastatic malignant neoplasm involving the esophagus. "Together, these data showed that FAT1 inhibited the cell proliferation, adhesion, and invasion of human esophageal cancer, which might be associated with the upregulation of PTPN14 and inhibition of Yap1 and Myc." (PMID 34712552, 2021). "FAT1 inhibited the proliferation, adhesion, and invasion of human esophageal cancer cell lines, which might be associated with the upregulation of PTPN14 and the inhibition of Yap1 and Myc." (PMID 34712552, 2021). "Cell clone formation assay also demonstrated that the FAT1 inhibited the cell viability of human esophageal cancer cell lines." (PMID 34712552, 2021). "Here, we studied the role of FAT1 and PTPN14 in the regulation of cell proliferation, adhesion, and invasion during esophageal cancer progression and the possible association with the Hippo pathway." (PMID 34712552, 2021). "Cell adhesion assay also demonstrated that the FAT1 inhibited the cell adhesion of human esophageal cancer cell lines." (PMID 34712552, 2021). "In this study, we identified FAT1 as a tumor-suppressor which can inhibit the proliferation, adhesion, and invasion of human esophageal cancer cell lines." (PMID 34712552, 2021). "The results demonstrated that FAT1 inhibited the proliferation of human esophageal cancer cell lines." (PMID 34712552, 2021). "In this study, we examined the expression levels of Yap1, PTPN14, and FAT1 in human esophageal cancer cell lines and tissues." (PMID 34712552, 2021). "FAT1 knockdown may enhance stemness and ABCC3-associated cisplatin resistance in esophageal cancer cells via the Wnt/β-linked protein signaling pathway." (PMID 37147285, 2023). "The result demonstrated that FAT1 inhibited the invasion of human esophageal cancer cell lines." (PMID 34712552, 2021). "The results suggested that PTPN14 and FAT1 could regulate malignant progression and chemotherapy resistance of esophageal cancer based on the Hippo signaling pathway." (PMID 34712552, 2021). "Besides, immunohistochemistry was conducted on the same samples of esophageal cancer to analyze the relative protein expression of FAT1 and Yap1." (PMID 34712552, 2021). "FAT1 promotes the expression of PTPN14 and downregulates the expressions of Yap1 and Myc, to inhibit the proliferation, adhesion, and invasion of human esophageal cancer cell lines." (PMID 34712552, 2021). "Results showed that FAT1 and PTPN14 were downregulated, while Yap1 was upregulated in esophageal cancer tissues." (PMID 34712552, 2021). "Our results showed that FAT1 and PTPN14 are downregulated while Yap1 is upregulated in esophageal cancer tissues." (PMID 34712552, 2021). "We also studied FAT1/PTPN14 on proliferation, adhesion, and invasion characteristics of esophageal cancer cell lines by FACS, clone formation assay, and the Transwell method." (PMID 34712552, 2021). "However, how FAT1 and PTPN14 regulate the malignant progression and chemotherapy resistance of esophageal cancer is still unclear." (PMID 34712552, 2021). "qRT-PCR results showed that FAT1 was highly expressed in the SEG1, but low in TE13, suggesting FAT1 might inhibit the proliferation and progression of esophageal cancer." (PMID 34712552, 2021). "This study might provide a theoretical basis on the roles of FAT1 and PTPN14 in the occurrence and development of esophageal cancer." (PMID 34712552, 2021).
liver cancer (4 papers, 2015 to 2023). An epithelial or non-epithelial malignant neoplasm that arises from the liver. "Also, in liver cancer cases [liver hepatocellular carcinoma (LIHC); n = 371], FAT1 expression correlated inversely with infiltration of CD8+ T cells and dendritic cells while correlating positively with T-reg cell infiltration." (PMID 35720420, 2022). "Here, we found that high-level expression of GPC3 coincided with that of FAT1 in all the tested liver cancer cell lines (HepG2, Hep3B, and Huh7), and undetectable in normal liver tissues." (PMID 33420124, 2021).
microphthalmia (4 papers, 2019 to 2025). Congenital or developmental anomaly in which the eyeballs are abnormally small. "Compared to wild-type (WT) embryos FAT1−/− mouse exhibited microphthalmia." (PMID 30862798, 2019). "We here identified five unrelated families presenting with a new syndrome consisting of colobomatous microphthalmia, ptosis, and cutaneous syndactyly with or without glomerulotubular nephropathy, associated with homozygous frame-shift mutations in the FAT1 gene." (PMID 30862798, 2019).
myocardial infarction (4 papers, 2018 to 2023). Gross necrosis of the myocardium, as a result of interruption of the blood supply to the area, as in coronary thrombosis. "Omega-3 polyunsaturated fatty acid supported cardiac healing following myocardial infarction in fat-1 transgenic mice by regulating several apoptosis-associated miRNAs including miR-1a-3p." (PMID 35034631, 2022). "To determine whether a similar effect of endothelial FAT1 loss may also be seen in ischemia-induced angiogenesis in other vascular beds, we assessed endothelial cell density in the infarct zones 14 days after induction of acute myocardial infarction." (PMID 37031213, 2023). "In myocardial infarction of Fat-1 transgenic mice, miR-29c-5p was observed to be significantly upregulated." (PMID 34603374, 2021).
ovarian carcinoma (4 papers, 2018 to 2025). A malignant neoplasm originating from the surface ovarian epithelium. "Indeed, BRCA along with ovarian cancer (OV) showed the most positive correlations between FAT1 and range of immunomodulatory molecules including TGF-β and TGF-βR1." (PMID 40083689, 2025).
pancreatic adenocarcinoma (4 papers, 2014 to 2025). "Clinical utility of extracellular FAT1 domain has been established in pancreatic adenocarcinoma where soluble FAT1 ectodomain was found to act as serum biomarker." (PMID 33878524, 2021). "Lastly, we developed an ELISA-based assay able to measure the ectodomain of Fat1 and demonstrate that increased levels of soluble Fat1 can be detected in the serum of a proportion of patients with pancreatic adenocarcinoma as compared to unaffected controls." (PMID 24625754, 2014). "In silico analysis of publically available expression array data indicated overexpression of Fat1 as well as ADAM10 in pancreatic adenocarcinomas." (PMID 24625754, 2014). "Increased expression levels of Fat1 in pancreatic adenocarcinoma as compared to corresponding normal pancreatic tissue could be confirmed at the protein level by Western blotting." (PMID 24625754, 2014). "In conclusion ADAM10 mediated ectodomain shedding of Fat1 represents a novel mechanism producing a soluble form of this giant protocadherin that appears to be abundantly produced by human pancreatic adenocarcinoma cells in vitro and less so by their normal counterparts." (PMID 24625754, 2014). "Particularly, Fat1 was ranked among the 1% highest overexpressed genes and ADAM10 among the 5% highest overexpressed genes in pancreatic adenocarcinoma in three of five studies, respectively, with overexpression, although less pronounced, also detected in the other two studies." (PMID 24625754, 2014).
peripheral T-cell lymphoma (4 papers, 2020 to 2024). "In peripheral T-cell lymphoma, FAT1 was frequently mutated and accounted for a significant proportion (39%) of patients, which provided both prognostic and therapeutic implications." (PMID 35739249, 2022). "Some studies have also confirmed a worse prognosis in non-specific peripheral T-cell lymphomas with mutations in the FAT1 gene." (PMID 39054516, 2024). "Importantly, FAT1 mutations appeared to be clinically relevant in peripheral T-cell lymphomas not otherwise specified patients, being associated with poor prognosis." (PMID 31028364, 2020).
psoriasis (4 papers, 2014 to 2025). An autoimmune condition characterized by red, well-delineated plaques with silvery scales that are usually on the extensor surfaces and scalp. "In the present study, the fat-1 transgenic mouse was selected to expound the molecular mechanisms underlying n-3 PUFA effects in psoriasis, due to its advantages over other models, in eliminating confounding factors with regard to exogenous diets." (PMID 24718773, 2014). "Endogenous n-3 PUFA in a fat-1 transgenic mouse model protected against imiquimod-induced psoriasis-like inflammation via the IL-17/IL-23 axis." (PMID 35562873, 2022). "In conclusion, the present study provides further insight into the mechanisms involved in preventing inflammation in psoriasis-like mice by n-3 PUFAs using a fat-1 transgenic mouse model." (PMID 24718773, 2014). "In the present study, we used this fat-1 transgenic psoriasis mouse model to establish n-3 PUFAs as a therapeutic agent for psoriasis and to examine the molecular mechanisms underlying this effect." (PMID 24718773, 2014). "This study on fat-1 transgenic mice provided compelling evidence that the IL-17/IL-23 axis is a critical therapeutic target of inflammation in psoriasis and endogenous n-3 PUFAs are potential candidates for the prevention of hyperkeratosis and parakeratosis." (PMID 24718773, 2014). "In the present study, the effect of endogenous n-3 PUFAs on psoriasis-like lesions was investigated in a fat-1 transgenic IMQ-induced model." (PMID 24718773, 2014). "Furthermore, a murine imiquimod-induced psoriasis model in mice expressing fat-1, an enzyme found in Caenorhabditis elegans, which desaturases ω-6 PUFAs into ω-3 PUFAs, resulted in reduced Th17 cells in the skin." (PMID 39843435, 2025).
skin squamous cell carcinoma (4 papers, 2022 to 2024). A carcinoma arising from the squamous cells of the epidermis. "Recently, FAT1 deletion has been reported to promote a hybrid EMT state in mouse models of skin squamous cell carcinoma and lung tumors." (PMID 37460540, 2023).
acute myeloid leukemia (3 papers, 2012 to 2025). Acute myeloid leukemia (AML) is a group of neoplasms arising from precursor cells committed to the myeloid cell-line differentiation. "The role of FAT1 mutations in acute myeloid leukemia (AML) remains unclear, particularly regarding their impact on the chemosensitivity of AML patients." (PMID 40242237, 2025).
Arthritis (3 papers, 2018 to 2020). Inflammation of a joint. "As additional proof, endogenous production of ω-3 PUFAs in the fat-1 transgenic mice drastically attenuated arthritis as well as local and systemic levels of inflammatory cytokines following the establishment of RA, whereas the wild type control mice developed overt arthritis." (PMID 31611873, 2019). "A similar study using fat‐1 transgenic mice expressing Caenorhabditis elegans fat‐1 gene, which led to accumulation of PUFA, showed that these mice had a higher induction of Treg cells in vitro and in vivo, and lower clinical arthritis score." (PMID 33067808, 2020).
atherosclerosis (3 papers, 2022 to 2025). A disease characterized by the build-up of fatty material and calcium deposition in the arterial wall resulting in partial or complete occlusion of the arterial lumen. "Increased levels of 18-HEPE, secondary to EPA-supplementation or in fat-1-transgenic mice that convert ω6- to ω3-PUFAs, are associated with prevention of atherosclerosis and pathologic ventricular remodeling post-TAC." (PMID 37075982, 2023). "The function of SMC on atherosclerosis in Fat‐1 transgenic rabbit needs to be further studied in the future." (PMID 35040258, 2022). "In this study, atherosclerosis was induced in Fat‐1 transgenic rabbits and their littermate (WT) rabbits by feeding a high‐cholesterol diet containing 0.3% cholesterol and 3% soybean oil for 16 weeks." (PMID 35040258, 2022). "Fat‐1 transgenic rabbits that overexpress n‐3 PUFAs have been used to study the relationship between n‐3 PUFAs and atherosclerosis." (PMID 35040258, 2022). "In conclusion, n‐3 PUFAs improve atherosclerosis in Fat‐1 transgenic rabbits, and this process may depend on the increase in plasma HDL‐C and the decrease in the amount of SMCs in atherosclerotic plaques." (PMID 35040258, 2022). "In conclusion, endogenously synthesized n‐3 PUFAs can inhibit atherosclerosis in Fat‐1 transgenic rabbits, and this process may depend on the increase in plasma HDL‐C and the decrease in the amount of SMC in atherosclerotic plaques." (PMID 35040258, 2022). "Our results provide new insights into the multiple therapeutic potentials of Fat-1 to treat dyslipidemia, MAFLD, and atherosclerosis." (PMID 40052160, 2025).
breast tumor (3 papers, 2017 to 2025). "Rather, analysis of promoter methylation in FAT1 showed increases in breast tumor versus normal comparisons and consistently, FAT1 mRNA expression was negatively correlated with promoter methylation levels." (PMID 40083689, 2025). "Analyses based on microarray and RNA-seq technologies, respectively, revealed that ER positive breast tumors expressed the lowest FAT1 levels while those cases lacking ER showed higher FAT1 expression." (PMID 40083689, 2025).
cervical adenocarcinoma (3 papers, 2016 to 2022). An adenocarcinoma arising from the cervical epithelium. "In a prior retrospective study, we identified mutations in FAT1, ARID1A, ERBB2, and PIK3CA in whole-exome sequencing of 15 patients with cervical adenocarcinoma." (PMID 34203201, 2021).
chronic lymphocytic leukemia (3 papers, 2015 to 2025). "FAT1, an integral membrane protein regulating Wnt signaling that negatively regulates amyloidogenic processing in Alzheimer’s disease, has critical roles in solid tumors and has been demonstrated to be highly mutated in high-risk chronic lymphocytic leukemia." (PMID 40152254, 2025). "Moreover, among the mutated cadherin genes interacting with Wnt pathway, FAT1 (FAT atypical cadherin 1) was found mutated in solid tumors and chronic lymphocytic leukemia." (PMID 26046463, 2015). "FAT1 and its mutational inactivation have been linked to activation of the WNT pathway in solid tumors and to chemoresistance in chronic lymphocytic leukemia and could serve as an attractive therapeutic target." (PMID 25595890, 2015).
cutaneous squamous cell carcinoma (3 papers, 2021 to 2022). "For example, to explore the role of heparin-binding protein 17 (HBp17) and FAT1 in the progression of cutaneous squamous cell carcinoma, both adopted the knockout-first pattern and finally proved their mechanisms in promoting keratinization and deterioration, respectively." (PMID 36338621, 2022).